CDK13 (cyclin dependent kinase 13)
Diseases named in the same sentence as CDK13 in open-access papers (continued):
Sharing a sentence is not in itself a finding about the gene and the disease.
cancer (27 papers, 2012 to 2026). A tumor composed of atypical neoplastic, often pleomorphic cells that invade other tissues. "A recent clinical case report suggests a potential for increased cancer predisposition in individuals with germline CDK13 alterations." (PMID 41491919, 2026). "The dysfunction of CDK12 and CDK13 has been linked to cancer progression and therapy resistance, making them promising targets for new therapeutic agents." (PMID 41491919, 2026). "We also found that three genes – CENPF, GMNN and CDK13 – were frequently amplified in various human cancers and were significantly associated with several pathophysiological phenotypes in HCC." (PMID 22912832, 2012). "Additionally, we observed that CDK13 overexpression increased PNC prevalence a feature associated with cancer malignancy." (PMID 26886422, 2016). "The identification of the amplified genes CENPF, GMNN, and CDK13 in tumors provides new insight into the carcinogenesis process, and suggests that these genes can be used as novel cancer markers for the development of diagnostic, prognostic, and/or targeted therapies." (PMID 22912832, 2012). "Analysis of tumor versus normal tissue shows that CDK12 and CDK13 are frequently upregulated across multiple cancer types." (PMID 41491919, 2026). "This review highlights the biological rationale for targeting CDK12 and CDK13 in cancer, summarizes emerging therapeutic strategies, and identifies key opportunities for integrating these approaches into precision oncology." (PMID 41491919, 2026). "The specific contribution of the CDK12 paralog gene CDK13 in cancer remains inadequately understood." (PMID 39800748, 2025). "To date, research on CDK13 function has focussed on its role in cancer; amplification of CDK13 has been seen in tumour cells and CDK13 RNA over‐editing is a marker of poor prognosis in certain cancers." (PMID 39556044, 2025). "This study revealed that genetic or pharmacologic inactivation of CDK12 and its paralog CDK13 robustly activates stimulator of interferon genes (STING) signaling across multiple cancer types." (PMID 40955658, 2025). "Collectively, these results show that YJ9069 is a specific PROTAC degrader of CDK12 and CDK13 with potent growth inhibitory effects in subsets of cancer cell lines." (PMID 39353441, 2024). "SR4835 was used in mouse models in several studies to investigate the role of Cyclin K, CDK12, or CDK13 in cancers." (PMID 37626854, 2023). "This analysis also demonstrated differences between tCDK paralogs regarding their association with the prognosis of different types of cancer, as illustrated by opposite associations between CDK12 and CDK13 expression and KIRP prognosis." (PMID 36577800, 2022). "The HMGA2-KO MKN-45/MGC-803 cells together with their parental version were used to verify the anti-cancer efficacy of inhibiting HMGA2 and CDK13 associatively." (PMID 34513922, 2021). "CDK13 was significantly over-edited (c.308A > G) in tumor samples and functional analysis revealed that this editing event promoted cancer cell hallmarks." (PMID 34496885, 2021). "The recently discovered SR-4835 (a selective dual inhibitor of CDK12/CDK13) exhibits excellent anti-cancer therapeutic effects, especially when combined with PARP inhibitors (DNA-damaging chemotherapy) or anti-PD-1 (checkpoint inhibition)." (PMID 34513922, 2021). "CDK13 has been found to have the increasingly important role in cancer biomarkers and therapeutic targets in recent years, while it has detailed function and the underlying mechanism has not been clearly investigated." (PMID 34513922, 2021). "The role of CDK13 in cancers, such as ovarian cancer and hepatocellular carcinoma, has been focused on since 2018; however, no underlining mechanism has been reported." (PMID 34513922, 2021). "CDK13 is involved in pre-mRNA splicing and is a component of the perinucleolar compartment, which is primarily detected in solid tissue-derived cancer cells and rarely present in normal cells." (PMID 31883531, 2019).
cancer (continued). "Collectively, these results suggest that CENPF, GMNN, and CDK13 play a role in the tumorigenesis of human cancers." (PMID 22912832, 2012). "One can speculate that the role of CDK12 and CDK13 in regulating transcription in cancer cell lines is different from that in primary cells such as oocytes." (PMID 40148269, 2025). "Understanding the diverse functions of CDK13 could lead to more effective cancer therapies and improved patient outcomes." (PMID 39800748, 2025). "However, during the past two decades, increased efforts have been made to understand the functions of the catalytic subunits CDK12 and CDK13 in cancer biology." (PMID 37626854, 2023). "CDK12 and CDK13 are emerging as suitable targets in human cancers, including HGSOC." (PMID 37202753, 2023). "However, throughout this study we showed differences between CDK12 and CDK13 in terms of their effects on cancer cell fitness and their genetic co-dependencies." (PMID 36577800, 2022). "Although how the cell cycle checkpoint was regulated by these potential proteins has remained unclear, one point should be noticed: the inhibitor of CDK12/CDK13 might be a promising option for some types of cancer." (PMID 34513922, 2021). "ADAR1 and CDK13 have been demonstrated to act as oncogenes in several cancer types." (PMID 34496885, 2021). "TCGA database showed that CDK13 is amplified in different categories of cancer, indicating it could contribute to the tumorigenesis and development of cancer in humans." (PMID 34513922, 2021). "On the other hand, several recent studies have pointed out evidences that CDK13 could be involved in cancer." (PMID 26886422, 2016). "Our results suggest that inhibition of the amplified genes, CENPF, GMNN and CDK13, might be an effective new therapeutic strategy against human cancer." (PMID 22912832, 2012). "Furthermore, CDK13 gene has been shown to be amplified in several cancers." (PMID 26886422, 2016). "Furthermore, inhibitors of CDK13 could be promising anticancer therapeutics since targeting kinases in the cancer genome is a major strategy in anticancer-drug development." (PMID 22912832, 2012). "This review aims to synthesize current knowledge on Cyclin-dependent kinase 12 (CDK12) and Cyclin-dependent kinase 13 (CDK13), two transcriptional kinases with distinct and overlapping roles in gene regulation, genome stability, and cancer biology." (PMID 41491919, 2026). "Significant attention has been paid to the role that transcriptional CDKs play in cancer, including CDK7, CDK8, CDK9, CDK12, and CDK13." (PMID 40361480, 2025). "CDK12 and CDK13 have gained considerable attention as powerful oncogenic targets in the last years, especially for MYC-driven cancers." (PMID 37202753, 2023). "THZ1 is a highly selective covalent inhibitor of CDK7 with anti-tumor activity against multiple different types of cancer, but also inhibits CDK12 and CDK13 at higher concentrations." (PMID 36279270, 2022). "Thus CDK13 could play a major role in cancer and could be used as a cancer marker." (PMID 26886422, 2016). "Taken together, our results suggest that coincidently amplified CDK13, GMNN, and CENPF genes can play a role as common cancer-driver genes in human cancers." (PMID 22912832, 2012). "Moreover, the two cancer cell lines exhibited a different CDK13 WT/edit ratio, with a higher representation of the edited form in TPC1 cells and higher levels of CDK13 WT in Cal62 cells." (PMID 34496885, 2021). "CDK13 and FAM82B genes were amplified in 37.1% and 35.7% of cancer cell lines, respectively." (PMID 22912832, 2012). "Although CDK13 and FAM82B have not been well characterized in this context, they are associated with cell proliferation and chromosome stability in various cancer types." (PMID 22912832, 2012). "Knockdown of either CDK12 or CDK13 had no discernible effects on cell proliferation, underscoring the necessity of inhibiting both CDK12/13 function to suppress cancer cell growth." (PMID 39353441, 2024).
cancer (continued). "Whereas CDK19 and CDK20 are not essential in any of the cancer cell lines tested, there is a minor proportion of cell lines in which CDK8 (~ 3%), CDK10 (~ 1%), CDK12 (~ 27%) and CDK13 (~ 3%) are essential." (PMID 36577800, 2022). "Finally, we leverage paralog-based synthetic lethality to demonstrate that murine and human tumor tissue lacking functional CDK12 is sensitive to CDK13 inhibition and degradation—a finding with future clinical applicability in CDK12-mutant cancers." (PMID 39368479, 2024).
tumor (19 papers, 2012 to 2026). "Consequently, ARID1A-deficient tumor cells become more susceptible to CDK13 inhibitor treatment." (PMID 38835016, 2024). "Clinically, CDK13 overexpression correlates with advanced tumor stage, poor prognosis and aberrant lipid accumulation in patient-derived ccRCC tissues." (PMID 41680470, 2026). "In contrast to their oncogenic roles, CDK12 and CDK13 can also function as tumor suppressors in specific contexts, particularly in ovarian and metastatic castration-resistant prostate cancers." (PMID 41491919, 2026). "The transcriptional kinases CDK12 and CDK13 are central players in this process, but their influence is highly context-dependent, acting as oncogenic drivers in some tumors and tumor suppressors in others." (PMID 41491919, 2026). "In agreement with the subcutaneous allograft model, CDK13/12 degrader YJ1206 mitigated tumor cell dissemination." (PMID 40504161, 2025). "We, thus, depleted Cdk12, Cdk13, or both in tumor cells with siRNAs and assessed R-loops with the S9.6 antibody, the specificity of which was confirmed using RNase H treatment." (PMID 40955658, 2025). "In the absence of pharmacological treatment, ARID1A knockdown markedly decreased tumor clone development; under SR-4835 treatment, ARID1A-deficient cells demonstrated improved sensitivity to CDK13 inhibitors." (PMID 38835016, 2024). "This indicates that LUSC tumors with high PD-L1 mRNA expression drive the negative correlation observed between the E4/E6 mRNA ratio and CDK13 mRNA expression in the group of LUSC tumor samples." (PMID 38132164, 2023). "In our immunochemistry staining result, we found that there is a strong CDK13 staining in the stromal tumor micro-environment." (PMID 33390186, 2021). "We depleted Cdk12, Cdk13, or both in the Myc-CaP tumor model (top)." (PMID 40955658, 2025). "Importantly, the sensitivity of ARID1A-deficient tumor cells to SR-4835, a CDK12/CDK13 inhibitor, suggests a promising therapeutic approach for individuals with ARID1A-mutant tumors." (PMID 38835016, 2024). "CDK13 regulates gene transcription and co‐transcriptional processes by phosphorylating the C‐terminal domain of RNA polymerase II, and its selective inhibitor shows promising effects on tumor regression." (PMID 36495130, 2023). "We hypothesize that the high expression of CDK13 in stromal tumor micro-environment may be beneficial to the migration of PCa cells." (PMID 33390186, 2021). "In addition, we detected the expression of E2F5, CDK13 and p21 in the xenograft tumor tissues by Western blot analysis." (PMID 33390186, 2021). "Importantly, when we analyzed the WT and edited forms of CDK13 by RT-PCR and Sanger sequencing in PTC and contralateral normal tissue from 6 patients, we found a significantly higher level of edited CDK13 in the tumor tissue samples." (PMID 34496885, 2021). "As we observed, edited Q103R CDK13 stimulates a stronger cell proliferation and migration phenotype than WT CDK13 and, probably because of this, CDK13 editing might be an efficient mechanism contributing to tumor progression and aggressiveness." (PMID 34496885, 2021). "Furthermore, the high correlation between copy numbers of CENPF, GMNN, and CDK13 suggests that these three amplified genes utilize and/or share the same tumor-development pathway." (PMID 22912832, 2012). "No mutations in CDK12 and CDK13 genes were detected in these HGSOC tumor specimens or PDOs." (PMID 37202753, 2023). "Sequestering CDK13 in PNC could be one of the mechanisms of splicing alteration in tumour cells." (PMID 26886422, 2016).
tumor (continued). "Interestingly, the oncogenic activity of these genes (excluding FAM82B) was highly correlated with gene-copy numbers in tumor samples (correlation coefficient, r>0.423), indicating that amplifications of CENPF, GMNN, and CDK13 genes are tightly linked and coincident in tumors." (PMID 22912832, 2012). "Genetic or pharmacological disruption of the CDK13-METTL16-ACLY axis synergistically suppresses lipid deposition, tumor growth and metastasis in vitro and in vivo." (PMID 41680470, 2026). "Combining cyclin K/CDK12/CDK13 degrader, NCT02, with oxaliplatin and irinotecan exhibited synergistic anti-tumor effects in metastatic CRC cells." (PMID 41491919, 2026). "Our results define CDK12 as a key tumor suppressor in tubo-ovarian HGSC and highlight CDK13 targeting as a promising therapeutic approach in CDK12-inactive disease." (PMID 40504161, 2025). "For example, several kinases with consistently more signal in the tumor samples relative to the matched controls include: AurA, CHED (CDK13), JAK3, p38α, CHK1, ITPK." (PMID 27031502, 2016). "In addition, because no somatic point mutations in CDK13, GMNN, or CENPF genes were detected in primary tumor tissues, we think that the oncogenic effects of these genes are mainly due to alterations in gene copy numbers, particularly gene amplification." (PMID 22912832, 2012).
cardiac disease (2 papers, 2017 to 2020). "For example, while CDK13, CHD4, KDM5A, and SCN10A are related to familial heart disease, CFH, DGUOK, and POLE are related to familial vascular disease." (PMID 31941532, 2020).
infection (2 papers, 2013 to 2023). The state of being infected such as from the introduction of a foreign agent such as serum, vaccine, antigenic substance or organism. "Of the 17 HPK genes identified important for A/WSN/33 replication, six (CDK13, HK2, NEK8, PANK4, PLK4, SGK3) emulated the phenotype following A/New Caledonia/20/99 infection, i.e. increased or decreased virus replication as measured by influenza NP localization and influenza M gene levels." (PMID 23805279, 2013).
adenocarcinoma (1 paper, 2025). A common cancer characterized by the presence of malignant glandular cells. "Elevated levels of CDK12 and CDK13, which form complexes with CCNK, were also associated with worse OS outcomes in patients with adenocarcinoma." (PMID 40075638, 2025).
autosomal dominant disease (1 paper, 2024). Autosomal dominant form of disease. "Cyclin-dependent kinase 13 (CDK13)-related disorder is a rare autosomal dominant disease caused by pathogenic variants in the CDK13 gene." (PMID 38910624, 2024). "CDK13-related disorder is a rare autosomal dominant disease, therefore, there is no gender preference for this disease." (PMID 38910624, 2024).
prostate (1 paper, 2021). "To clarify the role of the CDK13-circCDK13-miR-212/miR-449a-E2F5 axis in prostate tumorigenesis, we established PCa xenograft models by implanting PC3 cells stably knocking down circCDK13, E2F5 or both into nude mice." (PMID 33390186, 2021). "Our findings provide the first evidence that CDK13 upregulation-induced formation of the positive feedback loop among circCDK13, miR-212-5p/miR-449a and E2F5 contributes to prostate carcinogenesis and drug resistance." (PMID 33390186, 2021).
CDK13 also shares sentences with these, for which no sentence is quoted: neurodevelopmental disorder (2 papers); autism (1); autism spectrum disorder (1); cardiac arrest (1); cardiovascular malformations (1); ciliopathies (1); craniosynostosis (1); deafness (1); diabetes insipidus (1); endometrial cancer (1); Ewing sarcoma (1); Hearing impairment (1); Hemophagocytic Lymphohistiocytosis (1); kidney failure (1); optical atrophy (1); Ovarian Tumors (1); pseudohypoaldosteronism (1); septal defect (1); serous ovarian carcinoma (1); Strabismus (1); Wolfram syndrome (1).